TM7SF3 (transmembrane 7 superfamily member 3)
Description:
Involved in the inhibition of cytokine-induced death of pancreatic beta cells. Involved in the promotion of insulin secretion from pancreatic beta cells. Maintains protein homeostasis and promotes cell survival through attenuation of endoplasmic reticulum (ER) stress and the subsequent induction of unfolded protein response (UPR).
Tractability: Antibody: UniProt places it where antibodies can reach, with high confidence; its Gene Ontology location is reachable by antibodies, with high confidence; UniProt predicts a signal peptide or a membrane-spanning region. PROTAC: ubiquitination databases record sites on it; its protein half-life has been measured.
Gene: Protein-coding gene on chromosome 12 (26,971,579 to 27,014,507, reverse strand). Ensembl gene ENSG00000064115.
Subcellular location: Cell membrane
Subcellular location (Human Protein Atlas): Cytosol; Nucleoplasm
Gene Ontology:
Biological process: cellular response to unfolded protein; negative regulation of programmed cell death; positive regulation of insulin secretion
Cellular component: cytosol; extracellular exosome; nucleoplasm; plasma membrane
Genetic constraint (gnomAD): Loss-of-function variants: 51 observed, 52.53 expected, observed/expected ratio (o/e) 0.97, 90% interval 0.77 to 1.23. The upper end of that interval is the gene's LOEUF score, 1.23, which puts it in group 5 of 6, group 1 being the genes least tolerant of losing a copy. Missense variants: 531 observed, 606.43 expected, observed/expected ratio (o/e) 0.88, 90% interval 0.81 to 0.94. Synonymous variants: 240 observed, 237.22 expected, observed/expected ratio (o/e) 1.01, 90% interval 0.91 to 1.13.
Homologues: Orthologues: chimpanzee TM7SF3 (99% identical), macaque TM7SF3 (97% identical), dog TM7SF3 (86% identical), pig TM7SF3 (85% identical), guinea pig TM7SF3 (81% identical), rabbit TM7SF3 (79% identical), mouse Tm7sf3 (78% identical), rat Tm7sf3 (77% identical), tropical clawed frog tm7sf3 (55% identical), zebrafish tm7sf3 (51% identical).
Diseases named in the same sentence as TM7SF3 in open-access papers:
TM7SF3 is named in the same sentence as 4 diseases in open-access papers, as found by Europe PMC text mining. Sharing a sentence is not in itself a finding about the gene and the disease. The quoted sentences say what the papers report.
Hepatic fibrosis (2 papers, 2021 to 2025). The presence of excessive fibrous connective tissue in the liver. "TM7SF3 is located on the surface of HSCs and plays an important role in hepatic fibrosis caused by CssPLA2." (PMID 33691755, 2021). "In this research, the ability of CssPLA2 to bind TM7SF3 is tested, and we investigate how TM7SF3 influences the ability of CssPLA2 to cause liver fibrosis." (PMID 33691755, 2021). "TM7SF3, the receptor of CssPLA2, plays important roles in liver fibrosis caused by CssPLA2." (PMID 33691755, 2021). "Therefore, TM7SF3, which is the receptor of CssPLA2, contributes substantially to liver fibrosis caused by CssPLA2." (PMID 33691755, 2021). "TM7SF3, the receptor of CssPLA2, is expressed on the membranes of HSCs and may play important roles in liver fibrosis caused by CssPLA2." (PMID 33691755, 2021). "Additionally, TM7SF3, the receptor of CssPLA2, which is located on the surface of HSCs, is related to liver fibrosis caused by CssPLA2, and inhibition of TM7SF3 with a TM7SF3 antibody relieves liver fibrosis caused by CssPLA2." (PMID 33691755, 2021). "Therefore, we hypothesized that CssPLA2 may activate HSCs to cause liver fibrosis through activation of the NF-κB signalling pathway and that the receptor of CssPLA2, TM7SF3, plays an important role in this process." (PMID 33691755, 2021).
Intellectual disability (1 paper, 2023). "Furthermore, seven intellectual disability candidate genes, TM7SF3, STK38L, ARNTL2, ERGIC2, TMTC1, DENND5B and ETFBKMT have been identified." (PMID 37034680, 2023).
neurodevelopmental disorder (2 papers, 2023). A behavioral and cognitive disorder with onset during the developmental period that involves impaired or aberrant development of intellectual, motor, or social functions. "Putative position effect of TM7SF3 and the inclusion of STK38L and ARNTL2 in CNVs at 12p11.23 along with their sporadic variants reported in neurodevelopmental disorder (NDD) patients will likely explain their candidacy." (PMID 37034680, 2023). "The results identified one potential KS candidate gene (TSPAN11), seven candidate genes for the neurodevelopmental disorder (TM7SF3, STK38L, ARNTL2, ERGIC2, TMTC1, DENND5B, and ETFBKMT), and four candidate genes for KS with ID (INTS13, REP15, PPFIBP1, and FAR2)." (PMID 37034680, 2023). "As a result, we identified a dozen candidate genes: TSPAN11 as a potential KS candidate gene, TM7SF3, STK38L, ARNTL2, ERGIC2, TMTC1, DENND5B, and ETFBKMT as candidate genes for the neurodevelopmental disorder, and INTS13, REP15, PPFIBP1, and FAR2 as candidate genes for KS with ID." (PMID 37563198, 2023).
TM7SF3 also shares sentences with these, for which no sentence is quoted: lung adenocarcinoma (1 paper).